PPARGC1B (PPARG coactivator 1 beta)
Description:
Plays a role of stimulator of transcription factors and nuclear receptors activities. Activates transcriptional activity of estrogen receptor alpha, nuclear respiratory factor 1 (NRF1) and glucocorticoid receptor in the presence of glucocorticoids. May play a role in constitutive non-adrenergic-mediated mitochondrial biogenesis as suggested by increased basal oxygen consumption and mitochondrial number when overexpressed. May be involved in fat oxidation and non-oxidative glucose metabolism and in the regulation of energy expenditure. Induces the expression of PERM1 in the skeletal muscle in an ESRRA-dependent manner.
Synonyms: PERC; PGC1B; PPARAGCIβ; ERRL1; PGC-1(beta)
Tractability: Small molecule: a structure with a bound ligand is known. PROTAC: ubiquitination databases record sites on it.
Gene: Protein-coding gene on chromosome 5 (149,729,994 to 149,855,022, forward strand). Ensembl gene ENSG00000155846.
Subcellular location: Nucleus
Subcellular location (Human Protein Atlas): Nucleoplasm; Cytosol
Pathways (Reactome):
Gene expression (Transcription): MLL4 and MLL3 complexes regulate expression of PPARG target genes in adipogenesis and hepatic steatosis; Regulation of RUNX2 expression and activity
Developmental Biology: Transcriptional regulation of brown and beige adipocyte differentiation by EBF2
Metabolism: PPARA activates gene expression
Organelle biogenesis and maintenance: Transcriptional activation of mitochondrial biogenesis
Gene Ontology:
Molecular function: AF-2 domain binding; nuclear estrogen receptor binding; protein binding; transcription coactivator activity; RNA binding; nucleic acid binding; transcription coregulator activity
Biological process: estrogen receptor signaling pathway; positive regulation of transcription by RNA polymerase II; regulation of DNA-templated transcription; energy homeostasis; positive regulation of cold-induced thermogenesis; positive regulation of osteoclast differentiation
Cellular component: mediator complex; nucleoplasm; nucleus
Genetic constraint (gnomAD): Loss-of-function variants: 31 observed, 94.13 expected, observed/expected ratio (o/e) 0.33, 90% interval 0.25 to 0.44. The upper end of that interval is the gene's LOEUF score, 0.44, which puts it in group 1 of 6, group 1 being the genes least tolerant of losing a copy. Missense variants: 1,214 observed, 1,311 expected, observed/expected ratio (o/e) 0.93, 90% interval 0.88 to 0.97. Synonymous variants: 538 observed, 540.74 expected, observed/expected ratio (o/e) 0.99, 90% interval 0.93 to 1.07.
Homologues: Orthologues: chimpanzee PPARGC1B (99% identical), macaque PPARGC1B (96% identical), dog PPARGC1B (86% identical), guinea pig PPARGC1B (81% identical), pig PPARGC1B (78% identical), rabbit PPARGC1B (77% identical), mouse Ppargc1b (76% identical), rat Ppargc1b (76% identical), tropical clawed frog ppargc1b (41% identical), zebrafish ppargc1b (27% identical), Drosophila melanogaster srl (13% identical). Paralogues in human: PPARGC1A (25% identical), PPRC1 (21% identical).
Diseases named in the same sentence as PPARGC1B in open-access papers:
PPARGC1B is named in the same sentence as 116 diseases in open-access papers, as found by Europe PMC text mining. Sharing a sentence is not in itself a finding about the gene and the disease. The quoted sentences say what the papers report.
breast carcinoma (31 papers, 2011 to 2025). "The expression of miR-378 and PPARGC1B was downregulated in breast cancer, and higher expression of miR-378 is associated with better outcomes in ER-positive breast cancer." (PMID 38203358, 2023). "Studies showed that the PPARGC1B rs7732671 variant increases breast cancer risk and affects cancer progression." (PMID 36587194, 2022). "Genetic variants in PPARGC1A and PPARGC1B have been reported in breast tumors and were associated with familial breast cancer susceptibility." (PMID 33224957, 2020). "Nevertheless, both Wirtenberger and colleagues' study and our study support the association of genetic variation of PPARGC1B with particular subtypes of breast cancer." (PMID 21269472, 2011). "In particular, Wirtenberger and colleagues investigated the coding variant Ala203Pro of PPARGC1B and found it to be associated with familial breast cancer susceptibility." (PMID 21269472, 2011). "Importantly, the association of PPARGC1B as well as its synergistic interaction with ESR1 was only observed in breast cancer patients with ER-positive tumors, as would be expected according to the biochemical mechanism of interaction." (PMID 21269472, 2011). "We observed an inverse relationship between the mRNA levels of XBP1 and PPARGC1B in the TCGA breast cancer dataset." (PMID 38203358, 2023). "The expression of miR-378 and its host gene, PPARGC1B, is downregulated in tumour samples from breast cancer patients." (PMID 38203358, 2023). "PPARGC1A can promote tumor metastasis by promoting oxidative phosphorylation, while PPARGC1B can promote the proliferation of HER2-overexpressed breast cancer cells." (PMID 36177002, 2022). "Conversely, reduced expression of Runx1 in breast cancer cells leads to elevated expression of both pre-miR-378 and PPARGC1B, which is a host gene of miR-378, to create a FBL on that reduces cell migration and invasion." (PMID 32102656, 2020). "“Associations of genetic variants in the estrogen receptor coactivators PPARGC1A, PPARGC1B and EP300 with familial breast cancer”." (PMID 23216862, 2012). "Given the known modification of ER activity by PPARGC1B in cellular response to estrogen exposure, we investigated the genetic interaction between rs741581, rs2340621 and rs6895698 within PPARGC1B and rs7761846 within ESR1 in terms of modulating ER-positive breast cancer risk." (PMID 21269472, 2011). "Cross-correlation analysis of SSR1/RPL39L was found only in colon and lung cancers, and the cross-correlation of PPARGC1B/CDKN2A was found only in colon and breast cancers, R-values of breast, colon and lung data." (PMID 39940786, 2025). "Two genes have some association to cancer but not to CRC: PPARGC1B is a co‐activator for ESR1 and variants in the gene have been associated with increased risk for estrogen‐positive breast cancer." (PMID 30809968, 2019). "Women carrying both PPARGC1B (rs2340621) and ESR1 (rs7761846) risk genotypes (GA/AA and CT/CC) had a much higher risk for breast cancer than noncarriers (GG and TT) (OR = 1.94, P = 2.03 × 10-6)." (PMID 21269472, 2011). "However, there was no cross-correlation between SSR1/RPL39L in breast cancer, although a cross-correlation between SSR1/VARS, VARS/PPARGC1B, and PPARGC1B/RPL39L was found." (PMID 39940786, 2025).
Obesity (24 papers, 2013 to 2024). Accumulation of substantial excess body fat. "In the liver, overexpression of PPARGC1B has been linked to increased mitochondrial respiration and energy expenditure in mice, resulting in resistance to obesity." (PMID 38233814, 2024). "Previous study reported that PPARGC1B rs7732671G>C and rs17572019G>A variants were associated with the decreased risk of obesity." (PMID 28418876, 2017). "One can suggest that the greater reduction in brain Ppargc1b expression in mutants than in controls could be associated with more pronounced obesity in the mutants." (PMID 32132889, 2020). "The PPARGC1B rs7732671G>C and rs17572019G>A variants were in almost complete linkage disequilibrium in Caucasians (R2 = 0.958) and they were associated with the decreased risk of obesity." (PMID 28418876, 2017). "In fact, recent research into microRNA-based therapeutics inhibiting a constellation of genes, including Ppargc1b in mice, has shown beneficial results protecting against diet-induced obesity." (PMID 38027204, 2023). "A total of 175 genes including thermogenic markers (UCP2, CKMT2, and CITED1) and 5 BATLAS markers (PPARGC1B, ACO2, ACSF2, NNAT, and DMRT2) were expressed less in active beige adipocytes carrying FTO obesity-risk variant as compared to risk-free carriers." (PMID 37416800, 2023). "No functional data were available for the PPARGC1B variants (ClinVar), but variants in this gene have been associated with obesity in both pediatric and adult populations." (PMID 38027204, 2023). "PPARGC1B methylation was potentially associated with decreased obesity at 36 months but was not statistically significant." (PMID 32059710, 2020). "For example, PPARGC1B methylation had a potentially strong association with decreased obesity at 36 months but was not statistically significant." (PMID 32059710, 2020). "Furthermore, eight of the 17 CpG sites reside in genes (FSTL1, SORCS2, NRF1, DLC1, PPARGC1B, CHN2, NXPH1) that have prior known associations with obesity, diabetes, and the insulin pathway." (PMID 28068899, 2017).
Insulin resistance (14 papers, 2013 to 2024). Increased resistance towards insulin, that is, diminished effectiveness of insulin in reducing blood glucose levels. "The PPARGC1B gene, peroxisome proliferator-activated receptor gamma coactivator 1-beta isoform X2, is known to be involved in the Insulin resistance biological pathway (bta04931), as well as to regulate glucose homeostasis and mitochondrial biogenesis." (PMID 38419530, 2024). "In addition, for circFAT3 KD, genes related to insulin signaling and insulin resistance (PPARGC1A, SLC27A2, PPARGC1B, PRKCQ, GYS1, and IRS1) were the top hits." (PMID 36840844, 2023).
diabetes (11 papers, 2012 to 2026). "PPARGC1B (peroxisome proliferator-activated receptor gamma coactivator 1-beta) is a coactivator of PPARs associated with diabetes mellitus and type 2 diabetes mellitus, whose important paralog of this gene is PPARGC1A." (PMID 41559682, 2026). "For example, the PPARGC1B gene (rs61408734-T locus) is down-regulated in people with type 2 Diabetes Mellitus as well as in pre-diabetes." (PMID 41542229, 2024). "Specifically, the PPARGC1B and NXPH1 genes have been associated with childhood obesity in Brazil and with diabetes in the Mexican-Mestizo populations respectively." (PMID 28068899, 2017). "It has been reported that peroxisome proliferator-activated receptor gamma (PPARG) and peroxisome proliferator-activated receptor gamma co-activator 1 (PPARGC1) family (e.g. PPARGC1A and PPARGC1B) are key agents in the development and pathophysiology of type 2 diabetes mellitus (T2DM)." (PMID 28418876, 2017). "PPARGC1B belongs to the PGC-1 family, which act as coactivators in the dysregulation in diseases such as diabetes, obesity and cardiomyopathy in humans." (PMID 22607048, 2012).
Hepatic steatosis (10 papers, 2012 to 2025). Steatosis is a term used to denote lipid accumulation within hepatocytes. "PPARGC1β knock-out mice have altered diurnal activity rhythms and develop hepatic steatosis after high-fat feeding." (PMID 23951220, 2013).
heart failure (9 papers, 2015 to 2023). Inability of the heart to pump blood at an adequate rate to meet tissue metabolic requirements. "Nonetheless, individual deletion of Ppargc1a or Ppargc1b accelerates heart failure in response to increased workload imposed by transverse aortic constriction." (PMID 34360813, 2021).
type 2 diabetes (9 papers, 2008 to 2026). "Similar to our findings, ppargc1b mRNA levels were found to be decreased with age in a twin study investigating the susceptibility to type 2 diabetes." (PMID 24548546, 2014). "The human PPARGC1B gene (peroxisome proliferator-activated receptor-gamma coactivator 1 beta), encoding PGC-1β, localizes to chromosome 5q32, a region that shows linkage to type 2 diabetes." (PMID 23637848, 2013).
Sepsis (7 papers, 2010 to 2025). Sepsis is defined as life-threatening organ dysfunction caused by a dysregulated host response to infection. "Ppargc1a and Ppargc1b expression increase functional mitochondrial mass and preserved mitochondrial function, e.g. in skeletal muscle, is associated with better outcomes in sepsis." (PMID 21966468, 2011). "This includes the metabolic and mitochondrial biogenesis master co-activators, Ppargc1a (PGC-1α) and Ppargc1b (PGC-1β) in Staphylococcus aureus (S. aureus) sepsis." (PMID 21966468, 2011). "Thus mmu-mir-202-3p expression correlates with decreased Ppargc1a and Ppargc1b in this in vivo model of sepsis." (PMID 20657826, 2010). "This would translate to therapeutic potential if Ppargc1a or Ppargc1b gene activation could be shown to improve recovery or lessen mortality in clinical sepsis." (PMID 20657826, 2010). "Thus, our findings that Ppargc1a and Ppargc1b are co-regulated in response to sepsis, and that mRNA stability for each correlates inversely with the expression mir-202-3p, indicate that both may serve pro-survival functions in sepsis." (PMID 20657826, 2010). "The PGC family of transcriptional co-activators (PGC-1α [Ppargc1a], PGC-1β [Ppargc1b], and PRC [Pprc]) coordinates the upregulation of mitochondrial biogenesis, and Ppargc1a is known to be activated in response to mitochondrial damage in sepsis." (PMID 20657826, 2010).
melanoma (5 papers, 2018 to 2024). A malignant, usually aggressive tumor composed of atypical, neoplastic melanocytes. "In melanoma cells, downregulating PPARGC1A/PPARGC1B results in decreased OXPHOS activity, creating an acidic tumor environment and triggering autophagy." (PMID 33937013, 2021). "In a bivariate analysis combining the nevus results with a recent melanoma GWAS meta-analysis (12,874 cases, 23,203 controls), SNPs near GPRC5A, CYP1B1, PPARGC1B, HDAC4, FAM208B, DOCK8, and SYNE2 reached global significance, and other loci, including MIR146A and OBFC1, reached a suggestive level." (PMID 30429480, 2018).
gout (4 papers, 2017 to 2021). A condition characterized by painful swelling of the joints, which is caused by deposition of urate crystals. "A linkage between gout incidence and polymorphisms has been reported in PPARGC1B, which increased NLRP3 and IL-1β expression." (PMID 33926105, 2021). "Later on, an SNP screening of gout patients identified a missense SNP (rs45520937), which causes Arg265Gln (p.R265Q) substitution in the exon 5 of PPARGC1B (PGC-1β), a transcriptional cofactors of PPARγ." (PMID 33717162, 2021). "Rs45520937 of the PPARGC1B gene was associated with gout in a Chinese cohort, and the A allele of this SNP was found to significantly augment the expression of NLRP3 and IL-1β." (PMID 30123371, 2018). "In a study of a Chinese cohort, PPAR-γ co-activator 1B (PPARGC1B) gene variance permissive for inflammation was increased in those with gout, with the PPARGC1B risk A allele rs45520937 approximately doubling the risk of gout." (PMID 28818081, 2017).
depression (3 papers, 2009 to 2019). "Our data did weakly replicate a previously-reported association of depression with PPARGC1B rs7732671 (P=0.0235)." (PMID 23521777, 2013). "PPARGC1B rs7732671 was also associated with both depression and delayed sleep phase, further supporting the functional role of this SNP." (PMID 23521777, 2013). "In summary, these analyses point to several directions of interest without providing statistically rigorous and replicated evidence of SNPs associated with depression, apart from a modest replication of PPARGC1B rs7732671." (PMID 23521777, 2013). "Also, rs7732671 in PPARGC1B was associated with P = 0.023, with the minor allele being associated with depression." (PMID 19166596, 2009). "Furthermore, in our analysis, several DE miRNA targets were found to be associated with neuropsychiatric disorders, such as schizophrenia (TTN, SYNPO), depressive disorder (PPARGC1B, TIMELESS), and autism (TAF1, TRIO)." (PMID 31652596, 2019). "There were 3 SNPs in PPARGC1B significant in the meta-analysis including a previously-noted nominal association of rs7732671 with depression, herein replicated (P=0.024), but this SNP was not significant in the GAIN depression GWAS." (PMID 23521777, 2013). "PPARGC1A possibly binds to RORE sites both on NR1D1 and on ARNTL, and PPARGC1B may act similarly, perhaps providing a partial explanation for effects on both mania and depression, seeming opposites which are both aspects of bipolar disorder." (PMID 19166596, 2009).
lung cancer (3 papers, 2017 to 2025). A malignant neoplasm involving the lung. "In summary, poor survival is associated with PPARGC1B, EIF4E3, and SMAD9 low gene expression in breast, colon and lung cancer." (PMID 39940786, 2025). "Moreover, the downregulations of PPARGC1B, EIF4E3, and SMAD9 are associated with poor survival in breast, colon, and lung cancer patients." (PMID 39940786, 2025). "This study highlights the significant contribution of PPARGC1B, EIF4E3, and SMAD9 out of 11 RBP genes as prognostic predictors in patients with breast, colon, and lung cancers and their potential application in personalized therapy." (PMID 39940786, 2025). "Interestingly, most of the downregulated genes, including PPARGC1B, EIF4E3, and SMAD9, were classified with poor survival in breast, colon and lung cancer." (PMID 39940786, 2025).
brain tumor (2 papers, 2014 to 2015). "It is tempting to speculate thatthe decrease in PPARGC1B observed in our brain tumor samples couldparticipate in the increase in ROS formation and eventually impact on mtDNAmutations." (PMID 25791281, 2015).
colon cancer (2 papers, 2022 to 2025). "In colon cancer, most likely because of the lack of data, cross-correlation identified only three correlating groups (EIF4E3/MEX3A, SSR1/RPL39L, and PPARGC1B/CDKN2A)." (PMID 39940786, 2025).
gastric cancer (2 papers, 2022 to 2024). A primary or metastatic malignant neoplasm involving the stomach. "In addition, a Chinese population-based study has revealed that the single-nucleotide variants of PPARγ, PPARGC1A, and PPARGC1B may be related to the susceptibility factors of gastric cancer in an eastern Chinese population." (PMID 38495486, 2024). "The purpose of this study was to investigate the association of PPARγ, PPARGC1A, and PPARGC1B variants with the risk of gastric cancer (GC)." (PMID 36587194, 2022).
glioma (2 papers, 2015 to 2020). A benign or malignant brain and spinal cord tumor that arises from glial cells (astrocytes, oligodendrocytes, ependymal cells). "Regarding the metabolic co-activators PGC1α and PGC1β (encoded bythe PPAGC1A and PPARGC1B genes, respectively), PPARGC1Aexpression was significantly increased in ODIII and GL tumors, whereasPPARGC1B expression was robustly decreased in all gliomas." (PMID 25791281, 2015).
multiple myeloma (2 papers, 2018 to 2022). "In addition to FOXM1, LDHA is upregulated in myeloma via HIF1A (hypoxia inducible factor 1 subunit alpha) and PPARGC1B (peroxisome proliferator-activated receptor gamma coactivator 1 beta)." (PMID 35794249, 2022).
osteosarcoma (2 papers, 2011 to 2020). A usually aggressive malignant bone-forming mesenchymal neoplasm, predominantly affecting adolescents and young adults. "Kressler and colleagues also demonstrated that PPARGC1B indirectly co-activates tamoxifen-bound ERα, which cooperates with NCOA1 to enable tamoxifen agonism in kidney and osteosarcoma cell lines." (PMID 21269472, 2011).
retinal disease (2 papers, 2012). "Based on putative function and/or involvement in retinal disease, we selected 16 genes – Bach2, Cdr2, Dusp12, Esrrb, Gpsm2, Haus1, Kdm5b, Lman1, Lrp11, Lrrc2, Ncoa2, Plekha2, Ppargc1b, Trim36, Wisp1 and Zdhhc14." (PMID 22511886, 2012).
ankylosing spondylitis (1 paper, 2013). An autoimmune chronic inflammatory disorder characterized by inflammation in the vertebral joints of the spine and sacroiliac joints. "Our purpose is to examine the influence of PPARGC1B, RUNX3 and TBKBP1 polymorphisms on the susceptibility to and the severity of ankylosing spondylitis in Chinese ethnic majority Han population." (PMID 23637848, 2013).
bipolar disorder (1 paper, 2009). A disorder of the brain that causes unusual shifts in mood, energy, activity levels and the ability to carry out day-to-day tasks. "The association of NR1D1 rs2314339 with bipolar disorder and DSPS and the association of PPARGC1B Pro203Ala, rs7732671, with both bipolar and unipolar affective disorders appear the most likely to prove reliable." (PMID 19166596, 2009).